MYC (MYC proto-oncogene, bHLH transcription factor)
Diseases named in the same sentence as MYC in open-access papers (continued):
Sharing a sentence is not in itself a finding about the gene and the disease.
neuroblastoma (continued). "The mechanism for why RBM39 is especially essential in MYC-driven neuroblastoma is an important question to address in the future and has the potential to reveal new targets." (PMID 34788094, 2021). "Ciclopirox targets KDM4B, inhibiting MYC signaling pathways and tumor growth in MYC-driven neuroblastomas." (PMID 33801599, 2021). "Suppressing CDK7 and CDK9 activity has been known to substantially reduce MYC expression and downregulate MYC target genes in T cell acute lymphoblastic leukaemia, mixed-lineage leukaemia, neuroblastomas and small-cell lung cancers." (PMID 34944870, 2021). "It has been demonstrated that both β-catenin overexpression and downregulation promote an antineoplastic effect on MYC-amplified neuroblastoma." (PMID 34577571, 2021). "On the basis of above results, we concluded that indisulam-mediated degradation of RBM39 is a viable strategy to target pre-mRNA splicing in MYC-driven neuroblastoma." (PMID 34788094, 2021). "Here, we therefore aimed to investigate the molecular effects of DpC on a panel of neuroblastoma cell lines to evaluate its impact on some of the most prominent molecules (MYC oncoproteins, NDRG1, and EGFR) in neuroblastoma." (PMID 35008802, 2021). "Subsequently, other transcriptionally addicted malignancies, including MYCN-amplified neuroblastoma and MYC/MYCL-amplified SCLC showed also sensitivity to CDK7 inhibition." (PMID 33686962, 2021). "As presented earlier, inhibition of fatty acid synthesis in neuroblastoma cells in vitro led to reduced cell growth, increased cell death, downregulation of MYC(N), and neural differentiation." (PMID 33659885, 2021). "On the contrary, IGF2BP1 upregulation in MNA neuroblastoma is supported by previous studies in primary tumors, MYC/MYCN-driven transcriptional regulation and conserved oncofetal expression of the protein." (PMID 34026620, 2021). "Pairwise comparisons showed that, as expected, MYCN was significantly overexpressed in neuroblastoma datasets compared with the adult tumor datasets, whereas the inverse was seen for MYC." (PMID 33918978, 2021). "Sensitivity to BET inhibition is correlated to amplification and/or overexpression of the respective driver genes in both medulloblastoma and neuroblastoma, i.e., MYC and MYCN, respectively." (PMID 33668642, 2021). "Specifically, treatment with DpC proved to target some of the major molecular targets in neuroblastoma, namely the MYC proteins and both total and phosphorylated levels of EGFR." (PMID 35008802, 2021). "This novel mechanism for regulation of c-MYC expression warrants investigation in cancers other than neuroblastoma." (PMID 32409685, 2020). "For example, ~19% of high-risk neuroblastomas have MYCN amplification and high MYCN expression, whereas ~11% overexpress MYC and less than 0.5% highly express both." (PMID 33425720, 2020). "These demonstrated that OCT4 binds to the cis-regulatory sequences in the MYC enhancer in 13-cisRA-resistant neuroblastoma cells." (PMID 32409685, 2020). "NMYC amplification is a fundamental element of the aggressive form of neuroblastoma and there is evidence that MYC activation plays a role in the aggressive phenotype in hepatoblastoma as well." (PMID 32962010, 2020). "We found that MYC transcription factor was positively correlated with the MYCN amplification in neuroblastoma in TARGET dataset." (PMID 32593299, 2020). "Prior to selecting cell lines for MYCN and MYC profiling, we assessed RNA expression and protein expression across a subset of neuroblastoma cell lines." (PMID 32286315, 2020). "In the current study, we defined MK2 phosphorylation of OCT4 as a novel mechanism for oncogenic activation of MYC in neuroblastoma." (PMID 32409685, 2020). "As our results suggested a compensatory mechanism involving MYCN and c-MYC in MYCN-amplified neuroblastoma cells upon glutamine deprivation, we also performed the 3D colony-forming assay following c-MYC knockdown." (PMID 32483461, 2020).
neuroblastoma (continued). "In mouse and human neuroblastoma cells, TAMs are found to increase STAT3 activation in neuroblastoma cells, and up-regulates MYC oncogenes, a process associated with IL-6 independent expression." (PMID 33224886, 2020). "The positive enrichment of MYC transcription factor in MYCN amplified neuroblastoma tissues was also observed in GSE19274 and GSE85047 datasets." (PMID 32593299, 2020). "CDK12 plays an important role in promoting cancer cell growth, especially in cancers driven by dysregulated transcription factors, such as cancers dependent on MYC (neuroblastoma) and the EWS–FLI1 fusion oncoprotein (Ewing sarcoma)." (PMID 32570740, 2020). "Although developed in MYCN-amplified neuroblastoma models, this compound shows promising effects on cell cycle and MYC/MYCN stability." (PMID 33585252, 2020). "In the GSEA assay, we identified 75 MYC target genes which were up-regulated in MYCN amplified neuroblastoma tissues in TARGET dataset." (PMID 32593299, 2020). "MK2-mediated OCT4 transcriptional activation is a novel mechanism for activating the MYC oncogene in progressive disease neuroblastoma that provides a therapeutic target." (PMID 32409685, 2020). "MYCN belongs to the MYC transcription factor family and is amplified in approximate 25% of neuroblastoma patients." (PMID 32593299, 2020). "We identified 13 MYC target genes which were increased in neuroblastoma patients with MYCN amplification in TARGET, GSE19274 and GSE85047 datasets." (PMID 32593299, 2020). "Together, we have validated both MYCN and MYC ChIP-Seq antibodies for use in ChIP-Seq, as well as genome-wide occupancy profiles for histone markers and open chromatin across a cohort of neuroblastoma cell lines." (PMID 32286315, 2020). "Together, these data suggest that in some high-risk neuroblastomas that lack MYCN amplification, MYC can drive CAMKV transcription." (PMID 32211329, 2020). "Our discovery of c-MYC mediating resistance to 13-cisRA and being highly expressed in PD neuroblastoma suggests that MYC transcriptional activation occurs both in a subset of patients at diagnosis and likely more frequently in tumors at time of PD." (PMID 32409685, 2020). "As c-MYC was elevated in PD neuroblastoma cell lines and in those selected for resistance to 13-cisRA, we sought to demonstrate that c-MYC overexpression confers resistance to 13-cisRA." (PMID 32409685, 2020). "Protein expression of c-MYC, pOCT4S111, and pMK2T334 was significantly higher in neuroblastoma PDXs established at progressive disease compared with PDXs established at diagnosis." (PMID 32409685, 2020). "Using DNA editing technology, we show that stabilisation of p27Kip1 operated by Prozac in MYC-activated cells is essential for the anti-neuroblastoma activity of the drug." (PMID 31900399, 2020). "Collectively, our data suggest interplay between MYCN and c-MYC expression in MYCN-amplified neuroblastoma cells upon glutamine deprivation." (PMID 32483461, 2020). "Since MYCN amplification was associated with poor outcome in neuroblastoma, we next assessed the prognostic effects of the 13 MYC target genes which were up-regulated in MYCN amplified neuroblastoma." (PMID 32593299, 2020). "This mirrors what is already known in neuroblastoma cell lines and primary tumors in which the expression of MYC and MYCN are mutually exclusive." (PMID 31748534, 2019). "It has been previously demonstrated that MYCN is able to compensate MYC activity in neuroblastoma cell lines and primary tumors, a mutual regulatory loop existing between them." (PMID 31748534, 2019).
neuroblastoma (continued). "For instance, genes that lose directionality at high MYC levels were expressed at reduced levels in MYC-driven group 3 medulloblastoma and aggressive neuroblastoma compared to less aggressive sub-entities." (PMID 30928206, 2019). "Accordingly, CdK2 inhibition has been shown to slow down the growth of MYCN-amplified neuroblastoma cells and of other MYC-driven tumors." (PMID 31341534, 2019). "Finding a targeted therapy for MYC-activated tumors, including neuroblastoma, has provided an insurmountable challenge for cancer researchers for many years." (PMID 35582571, 2019). "Based on the MYC target gene signature, we identified FACT (facilitates chromatin transcription), encoding a histone chaperone, as a therapeutic target in neuroblastoma." (PMID 31396265, 2019). "Neuroblastoma cells expressing high levels of MYCN or c-MYC were significantly more sensitive to treatment with these compounds." (PMID 30542116, 2019). "Because these two subsets of neuroblastomas showed almost identical survival curves, we have combined them together and initially termed them MYC-driven neuroblastoma." (PMID 29464082, 2018). "One study reported that increased c-MYC and/or MYCN expression defines highly aggressive, MYC- driven neuroblastoma." (PMID 30237861, 2018). "For example, super-enhancer-associated genes include IRF4 and MYC in multiple myeloma, PAX5, MYC, and IRF4 in diffuse large B-cell lymphoma, MYCN and ALK in neuroblastoma, and CDK6, MYC, and EGFR in glioblastoma." (PMID 29724031, 2018). "The identified association between high risk MYC and MYCN driven tumors and elevated lipids in medulloblastoma and neuroblastoma is also notable." (PMID 29541417, 2018). "N-Myc expression exhibits the inverse correlation with c-MYC in neuroblastomas and that the low transcriptional level of Klf4 is related with the poor clinical outcome of neuroblastoma patients." (PMID 30053872, 2018). "This enrichment in the regulation of ribosomal proteins and rRNA, along with genes involved in protein synthesis and turnover, has been similarly shown for MYC-driven cancers such as neuroblastoma." (PMID 29799508, 2018). "It is known that high levels of NOXA expression can confer sensitivity to BCL2 inhibitors and is a likely explanation for the sensitivity of MYC- amplified neuroblastoma cell lines to these agents." (PMID 30326621, 2018). "Our present findings indicated that Bt2cAMP treatment inhibited mouse neuroblastoma cell proliferation, increased caspase 3 activity, and decreased c-MYC and HDAC8 levels." (PMID 30237861, 2018). "A similar approach based on MYC mRNA and miRNA levels correlation was previously applied in neuroblastoma." (PMID 30038718, 2018). "Given the interaction of MYC and the polyamine pathway, significant effort has been devoted to understanding the role of polyamines in supporting neuroblastoma initiation and progression." (PMID 30326621, 2018). "Beyond this somatic activation of polyamine synthesis, transcriptome analyses identified polyamine metabolism as coordinately deregulated by MYC in neuroblastomas." (PMID 29799508, 2018). "Polyamines play an important role in neuroblastoma in that they are cationic chaperones that support MYC activities through ionic and covalent mechanisms and are critical to initiating and maintaining the cancer phenotype." (PMID 30326621, 2018). "Neuroblastoma is a highly lethal pediatric malignancy of neural crest cells and a prototypical MYC-driven cancer." (PMID 29799508, 2018). "In a neuroblastoma cell line, MYC-MAX and MLXIP-MLX were found to cooperatively regulate transcription of a subset of genes involved in metabolism." (PMID 30054853, 2018). "The H3K9 demethylase, KDM4, has shown promise as a therapeutic target due to the discovery that KDM4B knockout in MYC-driven neuroblastoma cells resulted in downregulation of important MYC target genes, such as MIR17HG, CDC25A, SOX2, KITLG, VCAN, and SDC1." (PMID 28505071, 2017).
neuroblastoma (continued). "To validate the identified MYCN-specific gene expression pathway, we collected 41 unrelated neuroblastoma clinical samples, including 5 MYC–amplified and 36 wild type tissue blocks." (PMID 29137381, 2017). "Targeting the PI3K/Akt pathway using OSU03012 has proven advantageous in both neuroblastomas and medulloblastomas, showing a reduced MYC transcriptional output as well as affecting the stability of MYC proteins." (PMID 28333115, 2017). "We first validated that ML327 represses MYC signaling by demonstrating repression of N-MYC protein expression in the treatment of 4 MYCN-amplified neuroblastoma cell lines and C-MYC repression in 3 MYCN-single copy cell lines." (PMID 29207623, 2017). "In the present study we found that SF1126 displaces BRD4 from MYC transcriptional start site in IMR-32 neuroblastoma cell line." (PMID 28881723, 2017). "MYCN inhibition has previously been proposed to promote neuroblastoma cell differentiation, and we therefore treated LU-NB-3 cells with the MYC-MAX inhibitor 10058-F4." (PMID 28860499, 2017). "In both murine and human neuroblastoma cells, we found that TAMs increased STAT3 activation in neuroblastoma cells and transcriptionally up-regulated the MYC oncogene." (PMID 29207662, 2017). "Analysis of human neuroblastoma tumor specimens revealed that MYC up-regulation correlates with markers of TAM infiltration." (PMID 29207662, 2017). "For controls, we tested HCT116 cells that predominantly expressed MYC and Kelly neuroblastoma cells that expressed MYCN." (PMID 29028833, 2017). "Bromodomain inhibitors, such as JQ1, have demonstrated considerable preclinical promise for the treatment of MYC-driven malignancies, including neuroblastomas." (PMID 29207623, 2017). "In conclusion, we have identified the isoxazole-based compound ML327 as a novel inhibitor of the MYC signaling cascade in neuroblastoma." (PMID 29207623, 2017). "In neuroblastoma cohorts, ChIP analyses revealed that MYC and MYCN can bind at ABCG2 promoter, demonstrating a correlation between level of these transcription factors and ABCG2 mRNA." (PMID 29186899, 2017). "While the elevated expression of KDM4B in N-MYC amplified neuroblastomas is associated with poor clinical outcome, inhibition of KDM4B suppresses MYC function." (PMID 28505071, 2017). "MYC/MAX/MXD1 network has been shown to play a major role in the development of neuroblastoma and melanoma." (PMID 29383100, 2017). "Intriguingly, we also demonstrate that ML327 arrests neuroblastoma cell growth and transcriptionally suppresses MYC expression in neuroblastomas." (PMID 29207623, 2017). "The detected variants are located within the different domains of TIAM1 that signal to the upstream regulator RAS and downstream effector molecules MYC and RAC, which are all implicated in neuroblastoma etiology and progression." (PMID 28423360, 2017). "In the present study, we screened primary neuroblastomas by next generation sequencing and our results reveal that TIAM1 variants in the domains signaling to MYC, RAS and RAC significantly predict better prognosis in neuroblastoma patients." (PMID 28423360, 2017). "Deregulation of MYC family members is often associated with aggressive tumor behavior and therapy resistance, and MYC overexpression in amplified tumors represents a therapeutic challenge in many malignancies including neuroblastoma." (PMID 27769070, 2016). "MYCN, another MYC isoform, is amplified in pediatric neuroblastoma and has been shown to regulate metabolic pathways in a similar way as MYC." (PMID 27880818, 2016). "It has been shown, that T3-induced neuronal differentiation and growth arrest of neuroblastoma N2a-b cells is preceded by a decrease of c-MYC gene expression." (PMID 26799209, 2016).
neuroblastoma (continued). "Together, these results showed that SGO1 is elevated in MYCN- or MYC-overexpressing cancers, including neuroblastoma cell lines showing MYCN amplification." (PMID 27539729, 2016). "Therapeutically, THZ1 was shown to be highly effective in killing MYC-driven tumors, including neuroblastoma, small cell lung cancer, and triple-negative breast cancer." (PMID 27081479, 2016). "To validate this MYCN-driven neuroblastoma progression model, we evaluated the expression of 50 known MYC(N)-regulated miRNAs, summarized in a MYCN signature score." (PMID 25294817, 2015). "In neuroblastoma, aurora kinase A expression is correlated with MYC amplification and protects the MYC protein from degradation." (PMID 25884680, 2015). "MiR-9 is activated by MYC/MYCN-mediated E-cad downregulation resulting in metastases of neuroblastomas and breast tumors." (PMID 26110567, 2015). "As MYC(N) is a key driver of tumorigenesis not only in neuroblastoma, combination the conditional LSL-MYCN mouse with other cre-transgenic models bear the potential to also model tumorigenesis of other human malignancies." (PMID 25174395, 2015). "Recently, expression of miR-542-5p, which is repressed in MYC-amplified neuroblastomas was shown to be positively correlated with survival." (PMID 26682910, 2015). "Recent studies correlating microarray signals from MYC target genes with the clinical outcome of neuroblastoma found that MYC transcriptional signatures are predictive of disease outcome independent of MYCN amplification status." (PMID 25860940, 2015). "We show for the first time that the proliferation and clonal expansion of CD133+ neuroblastoma TICs relies on Spy1, and that Spy1 overexpression increases while its knockdown leads to decrease in c-MYC expression levels in this population." (PMID 25594028, 2014). "Since then BRD4 has been implicated in multiple myeloma as well as MYC driven tumors such as AML and neuroblastoma." (PMID 24796395, 2014). "OSU-03012, a 3-phosphoinositide-dependent kinase-1 (PDK1) inhibitor, destabilizes MYCN and MYC proteins in neuroblastoma cells." (PMID 25017515, 2014). "In contrast, we have recently demonstrated anti-tumorigenic effects of 10058-F4 in two tumor models of MYCN-amplified neuroblastoma, suggesting that direct MYC inhibition using a small molecule is achievable in vivo." (PMID 24859015, 2014). "For example, CDK/CK1 inhibitors have been shown to suppress MYC levels in human neuroblastoma cell lines." (PMID 24830942, 2014). "Instead, our data indicate that inhibition of MYCN by a BET inhibitor is more ubiquitous and potent than MYC in neuroblastoma." (PMID 24009722, 2013). "Three out of the four neuroblastoma cell lines with detectable MYC expression were examined; one cell line exhibited potent MYC suppression, the second showed intermediate effects, and the third was completely insensitive." (PMID 24009722, 2013). "We propose that MAX is involved in neuroblastoma progression, possibly increasing cell differentiation by means of regulating the availability of MYC:MAX heterodimers." (PMID 24349289, 2013). "Since potent anti-proliferative activity was observed for BET inhibitors in MYC-driven hematologic cancer models, we screened a panel of neuroblastoma cell lines, in which MYCN amplification is common, for effects on cell growth following I-BET726 treatment." (PMID 24009722, 2013). "Phosphopeptides from c-MYC, one of the major downstream targets of these pathways, was also highly abundant in the neuroblastoma cells." (PMID 24349301, 2013).